TLR4 (toll like receptor 4)
Diseases named in the same sentence as TLR4 in open-access papers (continued):
Sharing a sentence is not in itself a finding about the gene and the disease.
infection (continued). "Furthermore, absence of TLR4 also compromised iNOS gene expression and protein during the infection with Mtb strain 02-171." (PMID 23840651, 2013). "Of the 14 Th1 response genes tested, the expression levels of 8 genes (IL2, IFNG, CSF2, TLR4, CD4, IRF1, SOCS5 and STAT4) were significantly elevated at 2 weeks and several of these (IL2, IFNG, TLR4, CD4 and STAT4) had similar expression levels at 4 and 8 weeks post-infection." (PMID 23448601, 2013). "Whilst absence of TLR4 did not impact the growth of Mtb strain H37Rv in mice, lack of this receptor led to a marked increase in the lung bacterial burden of Mtb strain 02-171-infected mice within the first two weeks post-infection." (PMID 23840651, 2013). "Thus, TLR4 plays an important role in the defense against infections by Gram-negative bacteria that release LPS." (PMID 24025421, 2013). "While the number of lung pDCs was mostly similar between the TLR4−/− and WT mice, with the exception of late time points of infection, the number of pDCs in MLN was significantly higher in WT mice, compare to the TLR4−/− mice, during the acute phase of infection (day 5 p.i.)." (PMID 24205331, 2013). "Similarly, RAGE or TLR4 deficiency did not impact on neutrophil influx, except for modestly lower neutrophil numbers in BAL fluid of tlr4−/− mice harvested 72 hours after infection (P <0.05 versus Wt mice)." (PMID 24342460, 2013). "Both mice challenged with hMPV had peak viral titers at the lower limit of detection (<1.5 log10 TCID50/g tissue), assessed at day 4 p.i., indicating that overall the absence of TLR4 does not have a significant impact on hMPV replication, clearance and ability to respond to a secondary infection." (PMID 24205331, 2013). "Whether TLR4-mediated inhibition of β-catenin signaling in response to infection by Gram negative bacteria is a global phenomenon is not known." (PMID 24278135, 2013). "Absence of TLR4 did not impact cytokine expression in infections with H37Rv." (PMID 23840651, 2013). "Phagocytosis of the infecting Mtb and upregulation of TLR-2 and TLR-4 would result in the early production of IL-12, thereby contributing to the activation of lymphoid cells, consistent with our observation of elevated IL12B expression at 2 weeks post-infection." (PMID 23448601, 2013). "Alternatively, although the cytotoxicity of the sigE mutant is reduced, it may still be sufficient to establish lethal infections in the absence of TLR4 or TNF-α." (PMID 22897969, 2012). "Together uncontrolled infection and enhanced but ineffective inflammation induces increased severity and persistence of infection and disease that is most prominent in the absence of TLR2 combined with the presence of TLR4 i.e. in TLR2−/− compared to Wt and TLR4−/− or 2/4−/− mice." (PMID 22724018, 2012). "Since we found Acai PS has potent protective effects when given ≥24 h after infection, it would appear that Acai PS also signals through a receptor in addition to TLR4, and the low levels of LPS present in Acai PS are not responsible for the observed protection." (PMID 22438809, 2012). "TLR4 can also be activated by proteins released from dead and dying cells, and tissue matrix breakdown products in the absence of infection, including high-mobility group protein 1, surfactant protein A, fibronectin, fibrinogen, and hyaluronic acid oligosaccharides." (PMID 22251849, 2012). "In addition, we have demonstrated that TLR4 is not necessary for the increase in Ang4 post-infection with T. muris." (PMID 22970115, 2012). "TLR4 has been shown not to be essential for expulsion of T. muris and few worms remained in either C3H/HeJ or C3H/HeN mice at days 21 and 35 p.i. following a high-dose infection." (PMID 22970115, 2012).
infection (continued). "Massive lymph node enlargement has also been seen in wildtype but not TLR4 gene-targeted mice during infection with Salmonella typhimurium and others have shown a role for TLR-independent, TNF-independent or TNF-dependent involvement of mast cells in non-specific induction of lymph node enlargement." (PMID 21637808, 2011). "In addition, B220+ cells within the colon mucosa of TLR4−/− mice did not increase within 12 days following C. jejuni-infection." (PMID 21698299, 2011). "Furthermore, using a murine model of C. difficile infection we show that mice display increased severity of infection in the absence of TLR4." (PMID 21738466, 2011). "However, we found that neither TLR2 knockout nor TLR2/TLR4 double knockout mice exhibited differences in survival compared to WT mice using this infection model (unpublished data)." (PMID 22039448, 2011). "Hence, these results suggest that the lower NO production due to the absence of TLR4 expression during the early phase of infection with T. cruzi is responsible for the higher sensitivity observed in Tlr4−/− mice." (PMID 20442858, 2010). "The main findings of this study were the observations that high VT MV, in the absence of infection, induced up-regulation of TLR4 and down-regulation of IRAK3 and IκBα protein levels, resulting in an increase of pro-inflammatory cytokines levels in the lungs and in the systemic circulation." (PMID 20199666, 2010). "One simple explanation of our results is that the PTL subjects that exhibit an elevation of TLR4 in their accessible peripheral circulation may suffer from either a subclinical infection and/or a non-infectious inflammatory process." (PMID 20964862, 2010). "Since all previous mapping had been done in mice with intact Tlr4 genes, no QTL could have been detected at this locus even if Tlr4 does modulate the response to infection." (PMID 21085469, 2010). "In the murine UTI model, Tlr4 controls the innate immune response to Escherichia coli and Tlr4-/- mice develop ABU rather than severe infection suggesting that reduced mucosal Tlr4 function may protect the host against symptomatic infection." (PMID 20505764, 2010). "Because no infection is evident in this model, our observation raises the intriguing possibility that TLR4 may also function during inflammation, possibly in response to an endogenous ligand." (PMID 20497537, 2010). "Studies have shown that TLR4−/− and C3H/HeJ mice lost the function of TLR4 and could not clear effectively infection, acquired ABU status, suggesting that the absence of TLR4 signals can make an infected host appear asymptomatic." (PMID 21151974, 2010). "LPS treatment of uninfected THP-1 cells also co-induced the secretion of IL-1β and TNF to comparable levels (data not shown), suggesting that infection with vMyxM013-KO virus was as comparably robust at inducing these two cytokines as the triggering of TLR4 activation with LPS." (PMID 19851467, 2009). "Infection with TLR4-shRNA lentivirus could not completely inhibit PICP, hydroxyproline, α-SMA, and type I procollagen expression and also could not completely inhibit p-AKT and integrin β1 expression (as shown by the comparison between the TI and TI+L group)." (PMID 20017955, 2009). "We addressed whether or not this pathogen induces any TLR4-dependent recruitment of leukocytes to the lungs over the course of infection." (PMID 19169359, 2009). "Indeed, infection with helminths predicted low expression of TLR2 and, to a lesser extent, of TLR4." (PMID 18414649, 2008). "The protection that TLR4 affords is not due to effects on secretion of proinflammatory cytokines or type I interferon, and the receptor also does not uniquely regulate recruitment of white blood cells to the site of infection." (PMID 18802464, 2008). "Indeed, so far there is evidence that TLR4 affects both vaccine responses, as well as the course of infection with gram-negative bacteria and certain viruses, including respiratory syncytial virus." (PMID 18987746, 2008).
infection (continued). "We have shown that Toll-like receptor TLR4, which recognizes several bacterial, viral and self ligands, is upregulated on macrophages and mast cells (MC) immediately after CVB3 infection, resulting in a burst of proinflammatory cytokines in the heart 6 hours after infection." (PMID 23675015, 2007). "To obtain further insight into the involvement of TLR2 and TLR4 in the inflammatory response after infection with B. pseudomallei, we semiquantitatively scored lung histology slides generated from WT, TLR2 KO, and TLR4 KO mice at various time points after infection." (PMID 17676990, 2007). "And TLR4 is not important for protective immunity against experimentally induced melioidosis, whereas TLR2 is associated with the growth and dissemination of the infection, significantly contributing to distant organ injury and lethality." (PMID 17676990, 2007). "However, intracellular replication in TLR4, TLR2 and TLR4/2 knockout cells was not altered and the infection course and anti-Brucella immunity development upon BrLPS injection was unaffected in TLR4 mutant mice." (PMID 17637846, 2007). "Hence, it is conceivable that absent or insufficient LPS sensing by TLR4 makes this receptor redundant during infection in vivo with Legionella or Burkholderia." (PMID 17676990, 2007). "Interestingly, murine brucellosis was markedly exacerbated at weeks 3 and 6 after infection in animals that lacked functional TLR4 (C3H/HeJ) compared to C3H/HePas that paralleled the reduced gamma interferon production by this mouse strain." (PMID 16556309, 2006). "KSHV primary infection, expression of numerous KSHV genes, and abnormal activation of immune response in KSHV-infected cells including the alternative complement system and Toll-like receptor 4 and 5 (TLR4 and TLR5) pathways could also trigger inflammation (21, 28, –, 31, 38, –, 40)." (PMID 38117084, 2024). "In the presence of TLR2-rs5743708 and/or TLR4-rs4986791 polymorphisms, reduced binding affinity for E and S proteins, respectively may explain the inadequate immune response against SARS-CoV-2 that fails to control infection, worsening the disease outcome." (PMID 37766191, 2023). "Cathelicidins are also able to prevent activation of TLR2 and TLR4 signaling in macrophages by non-viable bacteria and their products at later stage of infection, resulting in reduced production of proinflammatory response that might protect local tissue from the injury." (PMID 37251385, 2023). "Therefore, it is necessary to explore whether MD-2 is important in response to some infections, but not others, or if TLR4 levels differ in one infection compared to another." (PMID 36506333, 2022). "Additionally, our pathway analysis revealed seven genes, IL-4, IFNγ, TLR4, CXCL8, IL-18, CSF2 and TNFα, are involved in the morphological and behavioral changes of macrophages, monocytes, granulocytes, and dendritic cells (DCs) and their recruitment into infection sites." (PMID 34753991, 2021). "Thus, in our model, released DAMPs or ROS from the liver may be the primary stimulators to produce NETs rather than platelet TLR4 as seen during infection." (PMID 32528475, 2020). "Similarly, E. coli K88 and mycotoxin zearalenone (ZEA) infection of IPEC-1 epithelial cell line was protected in the presence of mixed Lactobacillus strains (L. acidofilus ID11692, L. plantarum ID1253 and L. paracasei ID13239) by downregulating TLR-1, TLR-2 and TLR-4 gene expression." (PMID 32045425, 2020). "It was found in this study that HTV MV, in the absence of infection, with different levels of TLR4-targeted mice and treatments could result in different impacts on pro-inflammatory cytokine levels, such as IL-6 and MIP-2, in the BALF and in the systemic circulation." (PMID 32130574, 2020).
infection (continued). "Recent studies have revealed the existence of a multifaceted innate immune response triggered by toll-like receptor 4 (TLR4) on superficial bladder epithelial cells directed at clearing infection by Gram-negative pathogens, and maybe a less important or a different role of the adaptive immunity." (PMID 32821646, 2020). "While other models of infection during pregnancy have not yet been interrogated in a manner which allows for the disentanglement of fetal and maternal responses, there are strong similarities between the impact of malaria infection on placental TLR4 and the impact of a variety of other pathogens." (PMID 31178840, 2019). "In summary, the sequential collaboration of TLR3 and TLR4 to boost the inflammatory cytokine secretion of human monocytes, concomitant with the drastic triggering of cell death, may be a novel strategy for TLR-mediated host innate response to fight pathogen spread after infection." (PMID 29717111, 2018). "Because neuronal cells express TLR4 and C23 and TLR4 and C23 are capable of recognizing the RSV F protein, we tentatively hypothesized that RSV might enter neuronal cells via interactions of the F protein with TLR4 and C23, resulting in the proliferative infection of N2a neuronal cells." (PMID 29427996, 2018). "Moreover, mice pretreated with bacterial lipopolysaccharide (LPS), a product present on the exterior surface and shed by all Gram-negative bacteria, triggered a Toll-like receptor 4 (TLR4)-mediated antiviral response to protect the hosts from lethal infection with IAV." (PMID 29034326, 2017). "Furthermore, we identified the miRNomes pre- and post-infection with PRRSV strain LS-4 and concluded that ssc-miR-30d-R_1 targeted Toll-like receptor 4 (TLR4) of MARC-145 cells to suppress the production of immune cytokines by inhibiting the TLR4/MyD88/NF-κB pathway both in vitro and in vivo." (PMID 27117627, 2016). "Therefore, since TLR3 and TLR4 molecules contribute to the generation of a normal IFN response through activation of IRF-3, IRF-5, and IRF-7 after infection with neurotrophic virus, we tested whether the ablation of TLR3 and TLR4 molecules affected type I innate responses in JEV infection." (PMID 25188232, 2014). "Therefore, it is essential to explore whether MD-2 is important in the response to some infections, but not others, or that levels of TLR4 vary in one infection compared to another." (PMID 24282567, 2013). "Thus, TLR4 requirement is not absolute for NF-κB activation in response to CR infection." (PMID 24278135, 2013). "However, not all signaling pathways are inactivated by Yersinia during infection, and inhibition of c-KIT may lead to redirection to alternative signaling pathways, such as the LPS-activated CD14 and TLR4 signaling to p38 and JNK, to recover NF-KB-driven gene expression." (PMID 24206648, 2013). "Since the infection of TLR2/4 double-deficient mice with C. pneumoniae generated even more CD4+IFNγ+ T-cells, we conclude that in vivo antigen-presenting cells are not impaired in their ability to activate antigen-specific T-cells in the absence of TLR2 and TLR4." (PMID 22096480, 2011). "However, infection with TLR4-shRNA lentivirus could inhibit both the LPS-induced upregulation of integrin β1 and Akt phosphorylation, suggesting that LPS plays these roles through the PI3K-AKT pathway via TLR4." (PMID 20017955, 2009). "Our results showed that the infection did not change the mRNA expression of SOX2, NANOG, and POU5F1, but increased the mRNA expression of TLR4 and the cell surface expression." (PMID 40573358, 2025). "Later during infection, however, tlr4 mutant mice had elevated, albeit not significantly higher, amounts of TNF-α, IL-1α, and IL-6 relative to WT mice, consistent with persistent infection." (PMID 40817088, 2025). "TLR4 has been found in chorioamniotic membranes during PTB, even in cases where infection is not involved." (PMID 37867523, 2023).
infection (continued). "Extracellular Calprotectin acts as a DAMP by engaging both TLR4 and RAGE and also contribute to the response to infection via direct anti-microbial properties, notably, but not exclusively, due to its ability to withhold transition metals from pathogens." (PMID 38094743, 2023). "Infection with A66 resulted in TLR2-dependent TNFα release however, there was no significant impact of TLR4 on TNFα production." (PMID 36897919, 2023). "In these mice, GLY significantly reduced TLR4, but not HMGB1 or RAGE mRNA expression levels after infection." (PMID 36422579, 2022). "Upon the infection of RSV (strain A2) in primary human lung epithelial cells, the knocking down of TLR4, but not TLR3, TLR7, TLR8, or RIG-I results in a reduced expression of pro-IL-1β and IL-1β." (PMID 35308390, 2022). "LPS treatment did not potentiate infection in pASTROs and, unlike myeloid cells, did not decrease infection of the VSV G pseudotyped virus, suggesting that these cells are not responsive to TLR-4-mediated LPS signaling." (PMID 35975998, 2022). "TLR4 expression did not affect infection, as infection was comparable between 293/ACE2 and 293/TLR4/ACE2 cells." (PMID 35099061, 2022). "Next, we treated either ACE2‐positive or ‐negative 293 and 293/TLR4 cells with the primary SARS‐CoV‐2 isolate and determined infection and activation." (PMID 35099061, 2022). "After infection with E. chaffeensis, MIP-2 (CXCL2) and TNF mRNA induction in murine bone marrow derived macrophages was MyD88-dependent, but did not require TLR2 or TLR4." (PMID 33747981, 2021). "This is pertinent to former studies in which we established the need for TLR4 in resistance to P. aeruginosa by testing a resistant inbred strain (BALB/c) of mice, whose cornea does not perforate following infection." (PMID 34684184, 2021). "After 48 hours of infection, a decreased frequency of infected cells was observed following the neutralization of TLR2, 54% (31-62%), and TLR4, 45% (39-62%), versus 84% (72-91%) in non-neutralized monocytes (p<0.05)." (PMID 34691019, 2021). "In C. albicans infection, animals lacking TLR-4 showed lower levels of MIP-2 and KC leading to impaired neutrophil migration to the infection site." (PMID 33193308, 2020). "The variant was a cis-eQTL for IFNB1 after activation of the TLR1/TLR2, TLR4, and TLR7/TLR8 pathways, but not after infection with an influenza virus." (PMID 33147208, 2020). "First, we verified an impairment in neutrophil migration to the infection site in animals lacking TLR-2 and TLR-4 in both conidial and hyphal infections." (PMID 33193308, 2020). "These interactions are modulated by TLR2 and MyD88 signaling, but not by TLR4 engagement, after intranasal or intradermal LVS infection." (PMID 32745117, 2020). "In contrast, gene expression levels of TLR4 and TLR5 in all the tested tissues were unaffected by either NDV strains infection (data not shown)." (PMID 30070070, 2019). "In in vivo infection of 1-week-old chicken, a significant upregulation of the TLR4 and TLR5 genes in the spleen was observed in S. Gallinarum-infected chickens, but not in S. Typhimurium-infected chicken at 5 days post-infections." (PMID 31998655, 2019). "We performed LGG pretreatment and PR8 infection of TLR4-/- and C57BL/6 mice and found that LGG protection was abrogated when TLR4 was absent (35% LGG versus 24% sham, p = 0.21)." (PMID 31603951, 2019). "Tlr4−/− and Il1b−/− mice showed an attenuated phenotype, with markedly reduced background NK1R/SP expression and little or no response to infection." (PMID 30030504, 2018). "Our observation that PGLs limit the ability of macrophages to produce IFN-β upon TLR4 activation, irrespective of IFN-γ stimulation, is, therefore, particularly interesting to consider in the context of early immune responses to infection." (PMID 29403489, 2018).